CUL7 (cullin 7)
Diseases named in the same sentence as CUL7 in open-access papers (continued):
Sharing a sentence is not in itself a finding about the gene and the disease.
malignant glioma (1 paper, 2020). A grade III or grade IV glioma arising from the central nervous system. "However, the clinical significance, potential mechanism and upstream regulators of CUL7 in malignant gliomas remain to be determined." (PMID 32252802, 2020). "Both demonstrated efficient silencing of CUL7 in U87MG and U251 cells, two malignant glioma cell lines." (PMID 32252802, 2020).
Myocardial fibrosis (1 paper, 2020). "Collectively, our data demonstrate that CM-specific ablation of Cul7 restrains myocardial fibrosis and apoptosis upon pressure overload, and introduce CRL7 as a potential target for anti-fibrotic therapeutic strategies of the heart." (PMID 33351822, 2020).
myocardial infarction (1 paper, 2020). Gross necrosis of the myocardium, as a result of interruption of the blood supply to the area, as in coronary thrombosis. "Based on these data, pharmacological inhibition of cullin-7-based E3-ligases could represent a potential strategy to treat myocardial infarction." (PMID 33114658, 2020).
non-small cell lung carcinoma (1 paper, 2014). A group of at least three distinct histological types of lung cancer, including non-small cell squamous cell carcinoma, adenocarcinoma, and large cell carcinoma. "Cul7 is a novel anti-apoptotic gene whose overexpression has been associated with non-small cell lung carcinoma." (PMID 25474466, 2014).
Obesity (1 paper, 2017). Accumulation of substantial excess body fat. "Although we do not have suitable observation suggesting the involvement of S6K in the coffee extract-caused anti-obesity effect, it will be important to examine the influence of coffee extract on activity of S6K and CUL7, leading to the destabilization of IRS1." (PMID 28282409, 2017).
Protein deficiency (1 paper, 2023). "Protein deficiency of the CUL7 geneis associated with a delay in intrauterine development due toabnormal development of the placenta, which leads to intrauterinehypoxia." (PMID 36923475, 2023).
rectal cancer (1 paper, 2022). A primary or metastatic malignant neoplasm that affects the rectum. "TNM stage (P = 0.006) and high CUL7 expression (P = 0.001) were risk variables linked to poor outcomes for individuals with rectal cancer, according to multivariate Cox regression analysis." (PMID 36304472, 2022). "We selected cancer tissues and adjacent normal tissues from 100 patients with rectal cancer in Jiangmen Central Hospital for IHC analysis and found that cul7 was highly expressed in cancer tissues." (PMID 36304472, 2022).
yakut short stature syndrome (1 paper, 2020). "CUL7 mutations have been reported in 3-M syndrome and Yakuts short stature syndrome, the characteristics of which are profound growth retardation and endocrine disorders, with a normal mental status." (PMID 33130829, 2020).
cancer (15 papers, 2013 to 2025). A tumor composed of atypical neoplastic, often pleomorphic cells that invade other tissues. "CUL7 regulates cell cycle progression through CyclinA overexpression and affects the cell migration, which is a hallmark of cancer, influencing microtubule dynamics in breast cancer." (PMID 31712650, 2019). "The role the 3-M proteins have on XRCC5 function and DNA damage response is not characterised; however, there is evidence that elevated expression of CUL7 is associated with cancer progression and poor survival." (PMID 24711643, 2014). "CUL7, a gene composed of 26 exons associated with cullin 7 protein, is also an E3 ligase that is closely related to cell senescence, apoptosis, and cell transformation and also plays an important role in human cancer." (PMID 36304472, 2022). "Thus, further studies should explore the novel substrates of CUL7, especially substrates associated with cancer." (PMID 33130829, 2020). "MPP2 expression was significantly higher in cancer tissues compared to normal tissues (P < 0.01), while CUL7 expression was significantly lower in cancer tissues (P < 0.01)." (PMID 40260289, 2025). "While Cul7 exhibits increased expression in several types of cancer, it participates in tumor growth, invasion, and metastasis and is also associated with clinical stage and prognosis." (PMID 39852134, 2024). "As far as is known, Cul7 has been studied in various tumor types and has been found to play an important role in the initiation and development of various cancer types." (PMID 39852134, 2024). "Proteins belonging to the Cullin (Cul) family have critical roles in cancer, but few studies have been reported on Cul7 due to its characteristic molecular structure." (PMID 39852134, 2024). "Given the chaperone-like role of 14-3-3 proteins in promoting Cul7-mediated Eag1 degradation, it will be interesting to explore the tumor suppression potential of 14-3-3-targeting chemicals in Eag1-expressing cancers." (PMID 36717938, 2023). "We looked at the relationship between CUL7 expression and several survival outcomes for each cancer, including OS, DFI, PFI, and DSS, to better understand the prognostic value of CUL7 in pan-cancer." (PMID 36304472, 2022). "CUL7 is considered a potential new target for cancer therapy because they are upregulated in a variety of cancers." (PMID 36304472, 2022). "The correlation between the degree of immune cell infiltration and CUL7 expression was significant for the majority of cancer types." (PMID 36304472, 2022). "CUL3 and CUL7 are members of the Cullin ubiquitin ligase family and are involved in the regulation of various cancer-related biological pathways." (PMID 35463358, 2022). "Similar to the CUL7 scaffold proteins, the catalytic components Rbx1 and Skp1 are also regarded as an oncoprotein in most of the cancers." (PMID 33130829, 2020). "CUL7 exhibits increased expression in different human cancers, participates in tumor growth, invasion, and metastasis, and is associated with clinical stage and prognosis." (PMID 33130829, 2020). "Studies revealed that knocking down CUL7 inhibited cell proliferation, growth, invasion, and metastasis in cancer cells." (PMID 33130829, 2020). "Cullin (CUL) proteins have critical roles in development and cancer, however few studies on CUL7 have been reported due to its characteristic molecular structure." (PMID 33130829, 2020). "We systematically describe the recent major advances in understanding the role of the CUL7 E3 ligase in cancer and further summarize its potential use in clinical therapy." (PMID 33130829, 2020).
cancer (continued). "New roles for cullins in carcinogenesis will assuredly emerge in the near future since the relationship between cancer and some cullins (i.e., CUL7 and CUL9) is still a relatively new concept." (PMID 29594129, 2018). "Current studies mainly focus on the function of Cul7 in cancer." (PMID 39267786, 2024). "The mechanism of Cul7 in cancer still remains unclear because Cul7 plays a role in cell proliferation and invasion by regulating cell cycle and microtubule stability." (PMID 39852134, 2024). "It has also been shown that Cul7 promoted epithelial–mesenchymal transformation of cancer cells." (PMID 39852134, 2024). "There are currently two scenarios for the mechanism of action of CUL7 in cancer." (PMID 36304472, 2022). "CUL7 is found to be significantly expressed in breast, lung, hepatic, ovarian, and other malignancies and is connected to the development and incidence of several cancers." (PMID 36304472, 2022). "If these two proteins interact, we hypothesize that the Fbxw11-mediated regulation of the cell cycle and the NF-κB signaling pathway might be related to the interaction of Fbxw11 with CUL7 in these cancers." (PMID 33130829, 2020). "However, the role of CUL7 is explored in limited cancers and the mechanism of CUL7 is poorly elucidated, and studies on therapeutic targeting of CUL7 are lacking." (PMID 33130829, 2020). "CUL7 is one key factor in several cancers growth and metastasis, blocking the CUL7 ligase might be an effective therapeutic strategy for malignant cancers and their progress." (PMID 33130829, 2020). "Therefore, future studies may focus on the function of Cul7 in the progression and metastasis of various types of cancer and the detailed mechanism that controls the interactions between Cul7 and its complexes." (PMID 39852134, 2024). "Therefore, dysregulation of Fbxw8 or Fbxw11 might be an effective therapeutic approach for CUL7-related cancers." (PMID 33130829, 2020). "Thus, specific inhibitors preventing the binding of CUL7 with Rbx1 may be a novel therapeutic option for suppressing CUL7-related cancers." (PMID 33130829, 2020). "First, based on the Cancer Genome Atlas (TCGA), Genotypic-Tissue Expression Project(GTEx), Cancer Cell Line Encyclopedias(CCLE), and TISIDB database, the potential role of CUL7 in different tumors was explored." (PMID 36304472, 2022). "Previous work has examined the role of CUL7 and OBSL1 either in mouse studies or using gene overexpression or knockdown strategies in immortalised cancer cell lines." (PMID 24148222, 2013). "Finally, it is important to recognize that other E3 ubiquitin ligases, such as Cullin 7 (CUL7), can block caspase-8 degradation to enable cancer survival." (PMID 39996713, 2025). "In addition to GSEA analysis, a number of reports have demonstrated that CUL7 induces epithelial-mesenchymal transition (EMT), which plays a significant role in the invasiveness and metastasis of several cancers." (PMID 32252802, 2020). "CUL7 is a member of the CUL family of proteins; however, unlike that of other CUL family members, the role of CUL7 has not been studied in various types of cancer or systematically summarized." (PMID 33130829, 2020). "The vast majority of studies have shown that the high expression of CUL7 mainly affects the E3 ubiquitin pathway by forming Cullin (CUL)-RING E3 ubiquitin ligase (CRL), inhibiting the expression of cyclins, thereby promoting the proliferation of cancer cells and reducing apoptosis." (PMID 36304472, 2022).
cancer (continued). "In the TCGA dataset of this study, the expression of CUL7 was significantly increased in most tumor tissues including COAD compared with normal tissues, while the expression was decreased in some cancers such as ACC, KICH, and LAML, suggesting CUL7 may have oncogenic or tumor suppressor effects." (PMID 36304472, 2022). "Currently, the mechanism of CUL7 in cancer remains unclear, and no studies have addressed potential therapies targeting CUL7." (PMID 33130829, 2020). "To date, no study has reported the effect of the interaction of CUL7 and Fbxw11 in cancer." (PMID 33130829, 2020). "However, the role of CUL7 in these types of cancers is not clear, and whether CUL7 interacts with Fbxw11 in these cancers needs to be further explored." (PMID 33130829, 2020).
tumor (15 papers, 2008 to 2026). "CUL7 has been implicated in tumor initiation and progression." (PMID 38461173, 2024). "Furthermore, CUL7 expression is increased in multiple cancers, and is associated with tumor growth, invasion, and metastasis." (PMID 33130829, 2020). "Overall, our findings highlight the widespread up-regulation and functional significance of Cullin genes in CRC, with CUL5 and CUL7 emerging as key contributors to tumor progression and potential biomarkers or therapeutic targets." (PMID 42021323, 2026). "FBXW8 has been shown to be able to bind cullin protein 7 (CUL7), which exerts both tumor promotion and suppression in a context-dependent manner." (PMID 40375984, 2025). "The results identified a correlation between three tumor antigens—CUL7, ENO2, and MPP2—and both prognosis and APC infiltration in patients with COAD." (PMID 40260289, 2025). "Cul7 also exerts a tumor suppressor effect, as evidenced in part by the degradation of IRS-1 via the mTOR pathway." (PMID 39852134, 2024). "While studies show that Cul7 has tumor-suppressive effects, there are also studies suggesting the opposite." (PMID 39852134, 2024). "Future prospective studies focusing on CUL7 expression and tumor immune milieu will help to provide conclusive answers, allowing the development of immune-based anticancer therapies." (PMID 36304472, 2022). "In the correlation examination of tumor stage based on TCGA, the results showed that the expression of CUL7 in stage III was increased in COAD, KIRP, LIHC, MESO, TGCT, and THCA, stage II was increased in PAAD, and stage IV was increased in READ." (PMID 36304472, 2022). "While CUL7 also exerts a tumor-suppressive effect, as partially proven by the degradation of IRS-1, which is negatively mediated via the mTOR pathway." (PMID 33130829, 2020). "In contrast, CUL7 overexpression decreased the levels of tumour suppressors and upregulated downstream oncogenic factors." (PMID 32252802, 2020). "Among the existing studied CRL7-based E3 ligases, CUL7 exerts both tumor promotion and suppression in a context-dependent manner." (PMID 33130829, 2020). "In contrast, Cul7 overexpression appeared to promote tumor growth, invasion, and migration." (PMID 39852134, 2024). "IRS-1, the critical molecule downstream of insulin and insulin-like growth factor 1 receptor, can be ubiquitinated by Cul7 E3 ligase, suggesting that this tumor-suppressing activity may be related to Cul7-mediated degradation of IRS-1." (PMID 39852134, 2024). "In contrast, CUL7 overexpression promoted tumour growth, invasion and migration." (PMID 32252802, 2020). "However, only a few studies have reported which substrates are involved in the effect of CUL7 on tumor metastasis." (PMID 33130829, 2020). "A study in esophageal carcinoma (EC) showed that CUL7 protein expression was significantly higher than that in normal tissues, and was positively associated with tumor invasion and metastasis." (PMID 33130829, 2020). "FBXW8 forms a functional E3 ligase complex with cullin 7 to exert a tumor suppressive role." (PMID 30341246, 2019). "It will be interesting to determine in the future whether Cul7 may play a role in the regulation of Eag2-mediated tumor migration." (PMID 28098200, 2017). "In addition to the tumor suppressor role of Cullin 7 (Cul7), one of the proteins belonging to the Cullin (Cul) family, studies have also suggested that Cul7 may act as an oncogene under certain conditions." (PMID 39852134, 2024). "A previous study reported that CUL7 could degrade tumour suppressors, including p21 and p27." (PMID 32252802, 2020). "Transcriptomic profiling of TCGA datasets revealed significant up-regulation of CUL1, CUL2, CUL4A, CUL4B, CUL5, CUL7, and CUL9 in tumor tissues, with higher expression correlating with advanced stage and poorer survival, particularly for CUL5 and CUL7." (PMID 42021323, 2026).
tumor (continued). "Silencing the Cul7 gene in U87MG and U251 cells significantly inhibited tumor growth, invasion, and migration in vitro and in vivo." (PMID 39852134, 2024). "Gene silencing of CUL7 in U87MG and U251 cells significantly inhibited tumour growth, invasion and migration in vitro and in vivo." (PMID 32252802, 2020). "An in vitro investigation demonstrated that CUL7 promotes the EMT of EC1 cells, indicating the mechanism of EC tumor metastasis." (PMID 33130829, 2020). "Therefore, CUL7 may play a suppressive role in tumor growth and metastasis." (PMID 33130829, 2020). "The genes CCNB1IP1, CUL7 and E2F2 are involved in cell cycle control and cell growth and have expression levels in our study that promotes cell growth in the tumours from deceased patients." (PMID 18778486, 2008). "Furthermore, immunohistochemical analysis revealed that CUL7 protein expression was enhanced in HCC tumor tissues compared with normal liver tissues, especially in metastatic HCC tumor tissues, and was negatively correlated with long survival." (PMID 33130829, 2020). "Second post-CIR time point identified cullin 7 (CUL7) and last time point acyl-coa synthetase long chain family member 4 (ACSL4) with NF2, OBSL1 and YWHAE as highly connected components, all being described or hypothesized to play roles in tumor development." (PMID 35158950, 2022). "Furthermore, CUL7 silencing induced the downregulation of the expression of MMP2 and MMP9, matrix metalloproteinase (MMP) family proteins that play important roles in ECM degradation and in the migration and invasion of tumour cells." (PMID 32252802, 2020).
neurological disorders (1 paper, 2022). "Cul7 also has been shown to facilitate protein degradation in a disease-associated rEag1 mutant, indicating its possible participation in neurological disorders." (PMID 36553485, 2022).
CUL7 also shares sentences with these, for which no sentence is quoted: neuroblastoma (3 papers); choriocarcinoma (2); acromelic dysplasia (1); artery occlusion (1); Cerebellofaciodental Syndrome (1); developmental delay (1); endocrine disorders (1); fibrosis (1); Floating-Harbor syndrome (1); hypospadias (1); intestinal cancer (1); intrauterine growth retardation (1); lymph node metastasis (1); lymphocytic leukemia (1); Mowat-Wilson syndrome (1); ovarian cancer (1); retinal degeneration (1); Silver-Russell syndrome (1); stomach cancers (1); Ververi-Brady syndrome (1); vitiligo (1); X-linked mental retardation syndrome (1).